TFCP2L1 (transcription factor CP2 like 1)
Diseases named in the same sentence as TFCP2L1 in open-access papers:
TFCP2L1 is named in the same sentence as 27 diseases in open-access papers, as found by Europe PMC text mining. Sharing a sentence is not in itself a finding about the gene and the disease. The quoted sentences say what the papers report.
bladder cancer (7 papers, 2020 to 2025). "Here, we showed that CDK1 phosphorylation of TFCP2L1, a pluripotency‐associated transcription factor, orchestrated pluripotency and cell‐cycling in embryonic stem cells (ESCs) and was aberrantly activated in aggressive bladder cancers (BCs)." (PMID 31709755, 2020). "CDK1/TFCP2L1 axis is also involved in the induction of stemness characteristics and tumorigenic ability of bladder cancer cells." (PMID 36266723, 2022). "Another study has shown the role of CDK1 in phosphorylation of TFCP2L1 at Thr177 in embryonic stem cells of mice as well as human bladder cancer cells." (PMID 36266723, 2022). "CDK1 orchestrates a dual mechanism by directly engaging with the pivotal cancer stemness-related protein Sox2 to drive tumor initiation in melanoma, while simultaneously preserving tumor stemness characteristics and pluripotency through phosphorylating TFCP2L1 in human bladder cancer." (PMID 37743465, 2023). "However, CDK1 facilitates phosphorylation of TFCP2L1, activating embryonic stem cells in bladder cancer and driving tumorigenesis." (PMID 37196048, 2023). "In clinical samples of bladder cancer, activity of the CDK1/TFCP2L1 axis has been found to be associated with aggressive characteristics of tumors including advanced tumor grade, lymphovascular/muscularis-propria invasion, metastatic ability and poor clinical outcomes." (PMID 36266723, 2022). "The phosphorylation of transcription factor CP2-like 1 (TFCP2L1) by CDK1 at Thr177 promotes bladder carcinogenesis, and the tumorigenic potency of bladder cancer cells was reduced in a xenograft model when the level of TFCP2L1 phosphorylation was decreased." (PMID 35681641, 2022). "Thr177‐phosphorylation of TFCP2L1 by CDK1 stimulates pluripotency and cell cycling in embryonic stem cells and stemness features of bladder cancers, potentiating the tumorigenesis and aggressive behavior of bladder cancer." (PMID 31709755, 2020). "The physical and functional interaction between TFCP2L1 and CDK1 is conserved in human bladder cancer cells and modulates their proliferation and stemness features." (PMID 31709755, 2020). "The study provides the first direct experimental evidence that CDK1‐mediated phosphorylation of TFCP2L1 affects ESC function and promotes bladder cancer progression." (PMID 31709755, 2020).
melanoma (4 papers, 2023 to 2025). A malignant, usually aggressive tumor composed of atypical, neoplastic melanocytes. "Finally, high expression of Tfcp2l1 is considered a risk factor for survival in patients with glioma and testicular cancer, and a marker of poor prognosis for melanoma and liver tumors." (PMID 40813991, 2025). "Increased expression of TFCP2L1 as a result of blocking CXCR2 activity in mouse models of melanoma resulted in decreased expression of genes involved in tumor growth and increased expression of genes associated with tumor suppression." (PMID 40813991, 2025). "The mechanism for these changes in gene expression is in part due to induction of Tfcp2l1, a member of the TFCP2/TFCP2L1/UBP1 transcription factor subfamily that can serve as a pro-oncogenic factor in some tumors or in the case of melanoma, a tumor suppressor." (PMID 37270599, 2023). "As such, we probed the relationship between Tfcp2l1, differentiation along the melanocyte lineage, and cancer stem cells within melanoma." (PMID 37270599, 2023). "In addition to its role in maintaining stemness in a population of tumor cells, TFCP2L1 is likely also contributing to tumor suppressor in the melanoma models studied here." (PMID 37270599, 2023). "Thus, it is not clear that upregulation of TFCP2L1 is associated with an increase in a population of pluripotent cells in these melanoma tumors." (PMID 37270599, 2023). "Interestingly, after Cxcr2 ablation, Tfcp2l1, a key tumor suppressive transcription factor, was the only gene significantly induced with a log2 fold-change greater than 2 in these three different melanoma models." (PMID 37270599, 2023). "Finally, to define the activity of TFCP2L1 following CXCR2 perturbation, we performed chromatin immunoprecipitation and sequencing analysis (CHIPseq) on B16F0 tumorigenic melanoma cells following treatment with vehicle or SX-682." (PMID 37270599, 2023).
bladder (2 papers, 2022). "TFCP2L1 Thr177 phosphorylation is a central mechanism involved in regulating cell cycle progression and stemness features, which are important for bladder carcinogenesis." (PMID 35729325, 2022). "Recently, we reported that overexpression of transcription factor CP2-like protein-1 (TFCP2L1) and its phosphorylation at Thr177 by cyclin-dependent kinase-1 (CDK1) play key roles in regulating bladder carcinogenesis." (PMID 35729325, 2022).
bladder tumors (2 papers, 2020 to 2022). "TFCP2L1‐positive cells in bladder tumors displayed high expression levels of SALL4 and CD44 CSC markers." (PMID 31709755, 2020). "By contrast, p‐TFCP2L1 and CDK1 were expressed in 92.8 and 93.0% of the bladder tumor samples, respectively, with a wide range of H‐scores (0.0–231.0 with a median of 87.7 for p‐TFCP2L1, and 0.0–291.0 with a median of 100.0 for CDK1)." (PMID 31709755, 2020). "Notably, factors enriched in both ESCs and bladder tumors are well‐known members of TFCP2L1 network where they act as upstream regulators, interaction partners, and downstream targets." (PMID 31709755, 2020). "Next, we examined the expression levels of p‐TFCP2L1 and CDK1 and their co‐expression in normal urothelium of the urinary bladder and in a tissue microarray (TMA) construct generated from transurethral resections of bladder tumor (TURBT) specimens from 400 patients at our institute." (PMID 31709755, 2020).
hepatocellular carcinoma (2 papers, 2021). A malignant tumor that arises from hepatocytes. "Until now, researchers have discovered several novel circRNAs working as a miR-7 sponge, such as circ_0000735 in prostate cancer, circ-ITCH in osteosarcoma, circ-TFCP2L1 in breast cancer, and circ_0015756 in hepatocellular carcinoma (HCC)." (PMID 33673265, 2021). "The TFCP2/TFCP2L1/UBP1 TF subfamily is involved in various aspects of cancer development, including roles as pro-oncogenic factors in hepatocellular carcinoma as well as pancreatic and breast cancer." (PMID 33892791, 2021).
anaplastic thyroid carcinomas (1 paper, 2015). "TFCP2L1 is a crystallin, alpha B (CRYAB) gene promoter interacting transcription factor and lower expression of TFCP2L1 and CRYAB was revealed in anaplastic thyroid carcinomas compared to benign goiters." (PMID 25923053, 2015).
asthma (1 paper, 2025). "Expression of known ionocyte markers FOXI1, ASCL3, PDE1C, TFCP2L1 and CFTR in single cells was lost in hBECs from patients with neutrophilic asthma (and reduced in paucigranulocytic asthma) compared to healthy donors or eosinophilic asthma." (PMID 39358991, 2025).
chromophobe renal cell carcinoma (1 paper, 2023). Chromophobe renal cell carcinoma is a rare subtype of renal cell carcinoma, originating from the intercalating cells of the collecting ducts and macroscopically manifesting as a well-circumscribed, highly lobulated, solid tumor that is usually diagnosed at an early stage. "In the TCGA chromophobe renal cell carcinoma dataset, originating also from distal tubules, TFCP2L1 and MITF expression correlated with that of CDH1." (PMID 37236926, 2023).
clear cell renal cell carcinoma (1 paper, 2021). "In addition, TFCP2L1 has been reported to serve as a protective factor in clear cell renal cell carcinoma." (PMID 34123815, 2021).
Hypercalcemia (1 paper, 2026). An abnormally increased calcium concentration in the blood. "Interestingly, knockout TFCP2L1 mice showed reduced expression of distal nephron markers, possibly explaining the mild hypercalcemia and hypermagnesemia following increased sodium reabsorption in the thick ascending limb of the loop of Henle." (PMID 40569305, 2026).
kidney infection (1 paper, 2017). "For example, the decrease in PCs after Li treatment results in polyuria since PCs regulate water balance, while the decrease in ICs by Tfcp2l1 deletion enhances kidney infection since ICs mediate urinary acidification and the production of a number of antimicrobials including Lcn2/NGAL." (PMID 28577314, 2017).
lymph node metastasis (1 paper, 2020). "Co‐expression of p‐TFCP2L1 and CDK1 was an independent prognostic factor (P = 0.010) of cancer‐specific survival in multivariate analysis, in addition to age, lymph node metastasis, and muscularis propria invasion." (PMID 31709755, 2020).
teratocarcinoma (1 paper, 2020). A germ cell tumor characterized by the presence of an embryonal carcinoma component and a teratoma component. "p‐TFCP2L1 was specifically detected in a human teratocarcinoma cell line (NTERA2), but not in IMR90 primary fibroblasts, which served as positive and negative controls, respectively." (PMID 31709755, 2020).
thyroid cancer (1 paper, 2022). "TFCP2L1 is down regulated in renal and thyroid cancer cells." (PMID 35456988, 2022).
cancer (17 papers, 2015 to 2025). A tumor composed of atypical neoplastic, often pleomorphic cells that invade other tissues. "In line with the results of TCGA dataset analysis (Fig EV3D), p‐TFCP2L1 expression was more associated with cancer‐specific survival than SALL4 or CD44 expression in the BC patient cohort." (PMID 31709755, 2020). "Similarly, future studies will show if PRC2 based repression of Tfcp2L1/Lbp9 is critical for re-activation of dormant cancer cells causing tumor recurrence (a major cause for mortality in cancer patients)." (PMID 36230891, 2022). "Hypoxia, a common feature of solid tumors, triggers the reactivation of developmental genes like Tfcp2l1, enabling cancer cells to dedifferentiate and adopt stem cell-like properties." (PMID 40813991, 2025). "The gene Tfcp2l1 has emerged as a central player linking key processes in cancer biology: hypoxia, immortalization, dedifferentiation, and tumor progression." (PMID 40813991, 2025). "Originally identified for its role in maintaining pluripotency in embryonic stem cells, Tfcp2l1 has been found to reappear in various cancers, especially under conditions of low oxygen (hypoxia)." (PMID 40813991, 2025). "The role of TFCP2L1 in driving expression of epithelial genes was reinforced by analyses of the Cancer Cell Line Encyclopaedia (CCLE) showing positive correlation between TFCP2L1 (and also OVOL2) and EPCAM." (PMID 37236926, 2023). "We performed a subgroup analysis on CIS‐accompanying cases and observed a significant association between high co‐expression of p‐TFCP2L1 and CDK1 in the main tumor and frequent cancer‐specific death (P = 0.015)." (PMID 31709755, 2020). "The downregulation of RFX1 has been shown to predict poor prognosis in patients with small hepatocellular carcinoma, while TFCP2/TFCP2L1/UBP1 has been found to act as a TF in cancer." (PMID 32391054, 2020). "Furthermore, the association of TFCP2 and UBP1 with several cancer types, coupled with the parallels between certain mechanisms of placental development and tumor growth, have led to the recent study of TFCP2L1 as a prognostic marker for cancer." (PMID 40813991, 2025). "However, studies conducted to date reveal that the role of TFCP2L1 in cancer is diverse, as in some tumor types it appears to act as a protective factor, while in others it is associated with a worse prognosis." (PMID 40813991, 2025). "Importantly, the results offer insights into the regulatory mechanisms, expression, and functional profiles of TFCP2L1, demonstrating again the key role of stemness‐related transcription factors in the modulation of the stemness features of cancer cells." (PMID 31709755, 2020). "Finally, 6 prognosis related genes were selected out by COX regression analysis, TFCP2L1 related to cancer-stem cell, probably contributes to chemotherapy efficiency." (PMID 26228058, 2015). "The identification of p‐TFCP2L1 and CDK1 expression and co‐expression as predictive markers of cancer‐specific survival could open the prospect of developing p‐TFCP2L1/CDK1‐based immunohistochemical prognostic markers that could be easily applied in the clinic." (PMID 31709755, 2020). "In patients with BC, high co‐expression of TFCP2L1 and CDK1 was associated with unfavorable clinical characteristics including tumor grade, lymphovascular and muscularis propria invasion, and distant metastasis and was an independent prognostic factor for cancer‐specific survival." (PMID 31709755, 2020). "High levels of co‐expression of p‐TFCP2L1 and CDK1 were associated with aggressive clinicopathological features, such as high tumor grade (P < 0.001) and frequent muscularis propria invasion (P = 0.041), distant metastasis (P = 0.040), and cancer‐specific death (P < 0.001)." (PMID 31709755, 2020). "Notably, p‐TFCP2L1 and CDK1 were highly expressed in tumor tissues of BC patients with aggressive clinicopathological features, and this expression was associated with significantly shorter cancer‐specific survival." (PMID 31709755, 2020).
cancer (continued). "Conversely, pluripotency transcription factors, including NANOG, POU5F1 (encoding OCT4), and TFCP2L1 (encoding LBP9), that control HERVH activity in human ES cells associated with HERVH-CALB1 expression in other cancer types, but not in LUSC." (PMID 37192000, 2023). "High levels of p‐TFCP2L1 expression were correlated with high tumor grade (P = 0.002) and high tumor stage (P = 0.022) as well as with frequent LVI (P = 0.042), muscularis propria invasion (P = 0.026), and cancer‐specific death (P = 0.001)." (PMID 31709755, 2020). "In cancer cells with high levels of p‐TFCP2L1, CDK1, SALL4, and CD44 levels were significantly higher than in cells with low expression of p‐TFCP2L1, suggesting that a subset of p‐TFCP2L1‐positive cells could represent a population of bladder CSCs." (PMID 31709755, 2020). "What is importantly is that TFCP2L1 probably contribute to the differentiation of cancer stem cells, as embryonic stem cell self renewal pathways converge on the transcription factor Tfcp2l1, and this never been reported before." (PMID 26228058, 2015). "However, regulation of expression levels, activity, and post‐translational modification (PTM) status of TFCP2L1 during early embryonic development and in adult pathologies such as cancer have not previously been investigated." (PMID 31709755, 2020). "For example, there are numerous parallels between placental development and cancer growth; therefore, investigating the roles of TFCP2, TFCP2L1, and UBP1 in the placenta may help us better understand their functioning in cancer, as is evidenced by the studies of various other proteins and pathways." (PMID 30241344, 2018). "TFCP2L1 is not expressed in normal adult testes, though it is in intratubular germ cell neoplasia unclassified (ITGCN, formerly known as carcinoma in situ, CIS), a non-invasive precursor lesion from which TGCT is widely accepted to originate." (PMID 29560096, 2018).
tumor (9 papers, 2020 to 2025). "Comparable observations were made between the TAL and RMC populations of the naive tumour with loss of TFCP2L1 activity and gain of MYC and NFE2L2/3 activity." (PMID 37236926, 2023). "Ectopic expression of wild‐type TFCP2L1 or the T177E phospho‐mimic variant stimulated tumor sphere‐forming ability and clonogenic potential in a limiting dilution assay irrespective of the BC cell subtype." (PMID 31709755, 2020). "Further evidence for this series of oncogenic events came from the fortuitous capture of tumour-associated TAL2/3 cells that displayed a pre-transformed state retaining TFCP2L1 activity, while at the same time showing MYC and YY1 activity accompanied by a hypoxia and stress signature." (PMID 37236926, 2023). "The molecular mechanism by which TFCP2L1 acts as a protective agent in this case involves blocking the infiltration of pro-tumor immune cells by inactivating the NF-κB pathway." (PMID 40813991, 2025). "And this Tfcp2l1-dependent transcription will be, at least partly, responsible for immortalization and dedifferentiation of mature tumor cells." (PMID 40813991, 2025). "A key mechanism for these transcriptional changes involves increased expression of Tfcp2l1, a predicted tumor suppressive transcription factor when Cxcr2 activity is blocked." (PMID 37270599, 2023). "Overexpression of ID2 suppressed the increase in tumor-sphere formation induced by TFCP2L1 overexpression." (PMID 35729325, 2022). "Similar to the immunostaining results of tumor tissues from BC patients, TFCP2L1‐expressing cells in xenograft samples showed a high concurrence with cells stained with the bladder CSC markers including CD44, KRT14, and SALL4." (PMID 31709755, 2020). "Understanding how Tfcp2l1 integrates signals from hypoxic stress and drives dedifferentiation could uncover new therapeutic targets aimed at reversing or halting tumor progression." (PMID 40813991, 2025). "When tumor formation was measured 4 weeks after transplantation, T24 cells expressing wild‐type or T177E TFCP2L1 exhibited a significantly higher tumor growth than control T24 cells, while cells expressing T177A TFCP2L1 or shTFCP2L1 had significantly reduced tumor growth." (PMID 31709755, 2020). "Next, we investigated whether CDK1 and TFCP2L1 affected stemness features of BC cells by examining tumor sphere‐forming and clonogenic capacities." (PMID 31709755, 2020). "In summary, we have shown that phosphorylation of TFCP2L1 at Thr177 by CDK1 is important for ESC pluripotency and cell cycle processes, and that its aberrant activation in adult bladder tissue is associated with tumor progression and poor prognosis of BC." (PMID 31709755, 2020). "Comparison of the TAL and RMC populations from the treated tumour revealed a transcriptional switch from high HOXB9 and TFCP2L1 activity in TAL1 cells, to high MYC, HIF1A, YY1 and NFE2L2 activity in RMC cells." (PMID 37236926, 2023). "TFCP2L1 is a member of the TFCP2/TFCP2L1/UBP1 subfamily of transcription factors that contributes to the maintenance of stemness in pluripotent stem cells and can also exhibit tumor suppressive activity and modulate differentiation." (PMID 37270599, 2023).
TFCP2L1 also shares sentences with these, for which no sentence is quoted: breast carcinoma (1 paper); diabetes (1); gastric cancer (1); head and neck tumor (1); kidney disorder (1); leukemia (1); ovarian carcinoma (1); Polyuria (1); renal cell carcinoma (1); renal medullary carcinoma (1); urothelial carcinoma (1).